GTF2IRD1P1 (GTF2I repeat domain containing 1 pseudogene 1)
Gene: Transcribed unprocessed pseudogene on chromosome 7 (66,815,836 to 66,833,026, reverse strand). Ensembl gene ENSG00000230583.
Diseases named in the same sentence as GTF2IRD1P1 in open-access papers:
GTF2IRD1P1 is named in the same sentence as 1 disease in open-access papers, as found by Europe PMC text mining. Sharing a sentence is not in itself a finding about the gene and the disease. The quoted sentences say what the papers report.
gliosarcoma (1 paper, 2019). A rare histological variant of glioblastoma (WHO grade IV) characterized by a biphasic tissue pattern with alternating areas displaying glial and mesenchymal differentiation (WHO). "An interesting translocation between RABGEF1 and GTF2IRD1P1 genes was discovered in three gliosarcoma samples." (PMID 30818875, 2019).